FOXP3 (forkhead box P3)
Diseases named in the same sentence as FOXP3 in open-access papers (continued):
Sharing a sentence is not in itself a finding about the gene and the disease.
enterovirus infection (2 papers, 2020). "Our findings of enterovirus infection associated down-regulation of FOXP3 in Treg cells combined with a deviation to an increased Th1 immunity provides evidence of a potential mechanism supporting the induction of autoimmune responses by an enterovirus." (PMID 33643278, 2020). "In contrast, FOXP3 expression was significantly decreased in highly activated (CD4+CD127−/loCD25+FOXP3high) regulatory T cells (TregFOXP3high) in the infants who had enterovirus infection during the preceding 30 or 60 days." (PMID 33643278, 2020). "In contrast to rhinovirus infections, enterovirus infections were followed by a decreased FOXP3 expression in Tregs, particularly in the population of TregFOXP3high cells, which represent highly activated Tregs." (PMID 33643278, 2020). "Our results suggest that rhinovirus and enterovirus infections modulate FOXP3 expression and Treg maturation differently during the first year of life: enterovirus decreases the FOXP3 expression while rhinovirus may increase FOXP3 expression." (PMID 33643278, 2020).
epilepsy (2 papers, 2024). A brain disorder characterized by episodes of abnormally increased neuronal discharge resulting in transient episodes of sensory or motor neurological dysfunction, or psychic dysfunction. "Foxp3 in glial cells has been demonstrated to serve a protective role in the pathophysiology of epilepsy." (PMID 39861097, 2024). "Currently, no research specifically investigates the impact of L. dentata oil and ethanol extracts on FoxP3+ regulatory T cells (Treg) in a rat model of epilepsy." (PMID 39861097, 2024).
erythroderma (2 papers, 2017 to 2023). "During RR and erythroderma, IFNγ + lymphocytes and IL-17+ lymphocytes (191 and 213 cells/mm2, respectively) outnumbered IL-4+ lymphocytes and FoxP3+ lymphocytes (25 and 121 cells/mm2, respectively) in the skin tissue." (PMID 29262820, 2017). "Our previous study of leprosy patients with severe RR (without erythroderma, RR group, n = 14) showed the opposite: FoxP3+ lymphocytes prevailed over IL-17+ lymphocytes (170 ± 23 vs. 114 ± 27 cells/mm2)." (PMID 29262820, 2017).
falciparum malaria (2 papers, 2009). "Because Foxp3 expression is directly correlated with Treg cell suppressor activity, our data suggest that Treg cell activity is increased in severe falciparum malaria." (PMID 19390618, 2009). "To determine whether this balance is maintained by classical regulatory T cells (CD4+ FOXP3+ CD127−/low; Tregs) we compared cellular responses between Gambian children (n = 124) with severe Plasmodium falciparum malaria or uncomplicated malaria infections." (PMID 19343213, 2009).
Fanconi anaemia (2 papers, 2018 to 2022). "Patients with a FOXP3 gene deficiency or Fanconi anemia were also found to already have a reduced SSC pool prior to gonadotoxic therapy, which makes them even more vulnerable to its toxic effects." (PMID 35360062, 2022).
fungal infection (2 papers, 2018 to 2023). "We believe that while the initial oral/fungal infection might have triggered the inflammation pathology, loss of Foxp3+ cells and concomitant increase in IFN-γ producers (Th1) and Th1∗ cells mainly contributed to gut pathology." (PMID 30197637, 2018).
germinoma (2 papers, 2018 to 2025). A malignant germ cell tumor arising in the central nervous system. "In germinomas, CD3+ and Foxp3+ cells strongly correlated with CTLA-4 expression (p<0.001), and CD4+, CD8+, and Foxp3+ cells with PD-1 expression (p<0.05)." (PMID 39958339, 2025). "This study examined expressions of PD-1 and PD-L1 in intracranial germinoma and characterized the subtypes of TILs showing surface antigens such as CD3+, CD8+, CD4+, and Foxp3+ using a quantitative evaluation method." (PMID 29617441, 2018). "In germinomas, CD3+, CD4+, CD8+, and Foxp3+ cells infiltrated at 13.49% (range: 0.40%-40.91%), 6.44% (range: 0.37%-15.39%), 4.69% (range: 0.37%-16.99%), and 1.75% (range: 0.06%-7.76%), respectively, with CD4+ T cell levels being significantly higher than CD8+ cells (p=0.010, data not shown)." (PMID 39958339, 2025). "The study revealed that germinomas exhibited significantly higher infiltration of CD4+ and Foxp3+ T cells compared to non-germinomatous GCTs (NGGCTs)." (PMID 39958339, 2025).
Graves ophthalmopathy (2 papers, 2015 to 2020). An autoimmune disorder of the EYE, occurring in patients with Graves disease. "Similarly, future studies should also distinguish GD with and without Graves' ophthalmopathy (GO); (v) the majority of our concluded studies were conducted in Asian population, only two studies investigated the genetic effect of Foxp3 polymorphisms in Caucasian population." (PMID 32612577, 2020). "The present study was designed to investigate the expression of mRNA of the immune regulatory molecules FOXP3, CTLA-4/CD28/CD80/CD86, and CD40/CD40L in the orbital tissues from patients who underwent orbital decompression due to Graves' orbitopathy to assess their role in the inflammatory process." (PMID 25653477, 2015).
haemophilia A (2 papers, 2018 to 2019). "Upon transfer of the FVIII-specific CD4+ FoxP3+ cells into hemophilia A mice, development of inhibitory antibodies in response to administering FVIII protein was completely suppressed." (PMID 30842776, 2019). "In this study, we hypothesized that forced FoxP3 expression in conventional/effector CD4+ T cells (Tconv/Teff) from hemophilia A mice that were immunized with FVIII would yield an enriched pool of FVIII specific suppressor Treg-like cells." (PMID 30842776, 2019). "We conclude that reprogramed FoxP3 expressing cells are capable of inducing the in vivo conversion of endogenous FVIII peripheral Tregs, which results in sustained suppression of FVIII inhibitors caused by replacement therapy in recipient hemophilia A animals." (PMID 30842776, 2019). "The lack of an MHCII tetramer system to identify and isolate FVIII specific Th2 cells in BALB/c mice limits the scope of this study to ascertain the effective minimum dose of antigen specific FoxP3+ cells required to suppress an inhibitor response in the hemophilia A experimental model." (PMID 30842776, 2019). "Therefore, we determined the frequency of both LAP+CD25−FoxP3− cells among circulating CD4+ T cells and LAP+ cells among circulating CD4+CD25+FoxP3+ cells in haemophilia A mice that received either preventive or interventional oral tolerance." (PMID 29106782, 2018).
IgA nephropathy (2 papers, 2020 to 2021). "We comparatively studied the immunohistochemical expression of FOXP3+ Tregs, CD4+ and CD3+ T cells in IgA nephropathy (IgAN), focal segmental glomerulosclerosis (FSGS), and membranous glomerulopathy (MGN)." (PMID 34336285, 2021).
IgG4-related disease (2 papers, 2012 to 2015). "The activation of Treg cells in IgG4-related disease is suggested by the high expression of the forkhead box P3 (FOXP3) mRNA in tissue by the infiltrates of CD4+CD25+ Treg cells at affected sites and by the increased number of CD4+CD25+ Treg cells in the blood." (PMID 26491451, 2015).
infectious colitis (2 papers, 2012 to 2019). A viral or bacterial infectious process affecting the large intestine. "At30 days PI, both groups of mice demonstrated elevated IL-10 and FOXP3 mRNA(for both P < 0.05), indicating the resolution phase ofthe infectious colitis." (PMID 22694805, 2012).
inflammatory skin disease (2 papers, 2007 to 2024). Inflammatory skin disorders covers a broad category that includes many conditions ranging in severity, from mild itching to grave medical health complications These disorders are common in people of all ages and races. "Notably, we found an increased percentage of Tregs (FOXP3, CTLA4) in LP skin (P = 0.02), similar to other inflammatory skin diseases." (PMID 39190494, 2024).
interstitial lung disease (2 papers, 2015 to 2018). A diverse group of lung diseases that affect the lung parenchyma. "In patients with interstitial lung disease, the FOXP3 (+)/CD3 (+) cell ratio and established fibrosis (EF) score were inversely correlated." (PMID 30713498, 2018).
Kawasaki disease (2 papers, 2022 to 2023). A rare inflammatory disease characterized by an acute febrile, systemic, self-limiting, medium-vessel vasculitis primarily affecting children. "It was verified that Kawasaki disease (KD) serum has high level of miR‐223‐3p and low level of FOXP3." (PMID 37506144, 2023). "In patients with Kawasaki disease, it is found that low levels of miR-155 and low numbers of Foxp3+ Treg cells, and elevated levels of miR-31 and IL-6 are present." (PMID 36185934, 2022).
kidney cancer (2 papers, 2020 to 2023). Primary or metastatic malignant neoplasm involving the kidney. "So, we constructed the 786-O orthotopic kidney cancer model to examine the effect of FoxP3 in RCC in vivo." (PMID 37569676, 2023). "In order to verify this result, we extended to additional tumors including specimens of colon and kidney cancer, and found that overexpression of PD-L1 on VECs was also associated with fewer CD8+ T cells and more FoxP3+ Treg cells in these two cancer tissues." (PMID 32366856, 2020). "Using an in vivo nude mice orthotopic kidney cancer model, we found that silencing FoxP3 could inhibit tumor growth." (PMID 37569676, 2023). "In addition, our nude mouse orthotopic kidney cancer experiments showed that the growth of ccRCC cells with FoxP3 knocked out was significantly inhibited compared to controls." (PMID 37569676, 2023).
large cell lymphoma (2 papers, 2011 to 2024). "They observed higher numbers of FoxP3+ Tregs in patients presenting with earlier stages of MF compared to patients suffering from advanced MF and presenting tumours or transformations into large cell lymphomas." (PMID 39682197, 2024).
latent infection (2 papers, 2011 to 2019). "Differential expression of Foxp3 in PBMCs was predictive of active TB versus latent infection." (PMID 21197439, 2011).
liver failure (2 papers, 2011 to 2023). A liver disease characterized by the liver losing or has lost all of its function. "HMGB1 plays predominant role in etiology of liver failure in chronic HBV individuals by impeding immunological activity of regulatory T cells and by down-regulating Foxp3 expression." (PMID 36895013, 2023). "Because the increase in Foxp3+ T cells in the liver-infiltrating lymphocytes of ACLF and CLF patients was not proportional with the increase in IL-17+ T cells, the Foxp3+ T cells could not negatively regulate the immune system and ultimately, this would cause liver failure." (PMID 21851644, 2011).
low grade glioma (2 papers, 2012 to 2019). A grade I or grade II glioma arising from the central nervous system. "We used real-time PCR to evaluate the mRNA expression of FOXP3 in 11 low-grade gliomas (LGG), 59 GB (55 primary and 4 recurrent) and 20 GB primary cell lines growing in culture as neurospheres (NS)." (PMID 23888189, 2012).
medullary breast carcinoma (2 papers, 2014 to 2023). An infiltrating breast carcinoma with a relatively favorable prognosis. "FoxP3 + regulatory T cells (Tregs) can suppress antitumor immunity, and the ratio of CD8 + to FoxP3 + cells may be predictive for the clinical outcome of medullary breast cancer." (PMID 36797662, 2023).
megacolon (2 papers, 2011 to 2012). "Chagas disease patients without megacolon presented with an increased concentration of Foxp3(+) cells in all colon layers compared with megacolon patients and noninfected individuals." (PMID 22529863, 2012).
metastasis (2 papers, 2016 to 2025). The spread or migration of cancer cells from one part of the body (where they first appeared) to another. "The univariate analysis indicated that tumor diameter, degree of tumor differentiation, TNM stage, depth of tumor invasion, lymph node metastasis, and the expression levels of PD-1, PD-L1, FOXP3, CD25, CD4, and CD8 were factors significantly influencing EC prognosis (P < 0.05)." (PMID 40587482, 2025). "Based on the factors selected by the multivariable Cox regression analysis, including tumor diameter, tumor differentiation degree, tumor invasion depth, lymph node metastasis, PD-1, PD-L1, FOXP3, CD25, CD4, and CD8 as independent variables, a nomogram was constructed." (PMID 40587482, 2025).
metastatic carcinoma (2 papers, 2014 to 2021). A carcinoma which has spread from the original site of growth to another anatomic site. "We retrospectively analyzed the expression of β-catenin and immune cell markers CD8 and FoxP3 in a cohort of metastatic carcinoma in the liver." (PMID 34257613, 2021). "To this end, we analyzed CD8 and FoxP3 immunohistochemical expression against β-catenin expression status of the tumor in a cohort of 52 liver samples with metastatic carcinoma." (PMID 34257613, 2021). "Immune-suppressive CD4+CD25+FoxP3+ T-reg accumulate in primary and metastatic cancers and can prevent treatment-induced immune responses, therefore T-reg depletion represents a promising therapeutic approach." (PMID 25034887, 2014).
metastatic colorectal cancer (2 papers, 2010 to 2012). "Within a clinical phase I/II combined chemoimmunotherapy trial of patients with metastatic colorectal cancer we assessed frequencies of FOXP3-expressing CD4+CD25high Treg cells in peripheral blood before initiation of therapy in comparison to healthy controls." (PMID 22276195, 2012).
metastatic prostate carcinoma (2 papers, 2016 to 2025). A carcinoma that arises from the prostate gland and has spread to other anatomic sites. "Indeed, in ipilimumab-treated metastatic prostate cancer patients, almost 50% of circulating FoxP3+ Tregs expressed the proliferation marker Ki67 indicating they were proliferating efficiently in vivo." (PMID 27509527, 2016). "The findings of this study emphasize FOXP3, CD163, and PD-1 as key indicators of immune modulation across primary and metastatic prostate cancer." (PMID 41179298, 2025).
myelodysplastic syndrome (2 papers, 2018 to 2021). A clonal hematopoietic disorder characterized by dysplasia and ineffective hematopoiesis in one or more of the hematopoietic cell lines. "Increased amount of Treg (CD4+ CD25hi Foxp3+) was also identified in patients with myelodysplastic syndrome (MDS), correlating with high-risk MDS and higher number of blasts in the BM." (PMID 33801964, 2021). "We have investigated the frequencies of regulatory T cells and the level of FOXP3 isoforms expression in peripheral blood of patients with myelodysplastic syndromes and found the significant reduction of regulatory T cells at all stages of the disease." (PMID 30405716, 2018).
myeloproliferative disorder (2 papers, 2021 to 2023). A clonal hematopoietic stem cell disorder, characterized by proliferation in the bone marrow of one or more of the myeloid (i.e., granulocytic, erythroid, megakaryocytic, and mast cell) lineages. "Since Treg-deficient animal models like Scurfy and Foxp3-deficient mice similarly exhibit myeloid expansion, we hypothesized that the myeloproliferative disorder observed in gDKO animals was due to Treg deficiency." (PMID 34343134, 2021).
myocardial ischemia (2 papers, 2018 to 2021). A disorder of cardiac function caused by insufficient blood flow to the muscle tissue of the heart. "Otherwise, to explore the CD25 + Foxp3 + Treg cells function in myocardial ischemia–reperfusion injury, which drive from BM-MSCs, we defined the significantly effects of adoptive transfer of BM-MSCs." (PMID 33906602, 2021).
myositis (2 papers, 2016 to 2025). "When comparing the proportions (% of total T cells), CD244+ cells (median 33.4 %, range 0–85.7 %) were present in approximately 10-fold higher proportion compared to FOXP3+ cells (median 3.4 %, range 0–71.1 %, p = 0.01) in the myositis muscle tissue." (PMID 27039301, 2016). "Muscle biopsy sections were utilized to study CD3+, CD244+ and FOXP3+ cells in myositis muscle tissue." (PMID 27039301, 2016). "The presence of FOXP3+ cells (referred as regulatory T cells) in muscle tissue of untreated myositis patients has also been reported previously." (PMID 27039301, 2016). "The fact that the master T cell regulator FOXP3 was downregulated in all myositis conditions might imply, that cell subpopulations other than T cells could cause the characteristic regulation observed in irMyositis39." (PMID 40759686, 2025). "In this study, we could demonstrate that CD244+ cells (a validated surrogate marker for CD28null T cells in myositis muscle tissue) dominate the T-cell infiltrates over FOXP3+ cells (a marker for regulatory T cells) in inflamed myositis muscle tissue." (PMID 27039301, 2016). "However, FOXP3+ Tregs have also been described in myositis muscle tissue." (PMID 27039301, 2016). "However, this is the first study which investigates the frequencies FOXP3+ in relation to the CD244+ cells and how their relative proportion is affected in myositis muscle tissue by immunosuppressive treatment." (PMID 27039301, 2016).
Neonatal sepsis (2 papers, 2022 to 2024). Systemic inflammatory response to infection in newborn babies. "In addition, GNT could upregulate Tregs and FOXP3 expressions in mice with neonatal sepsis and reduce the apoptotic rate of Tregs." (PMID 36162982, 2022).
Nephroblastoma (2 papers, 2016 to 2020). An embryonal neoplasm characterized by the presence of epithelial, mesenchymal, and blastema components. "In our study, levels of the TIL markers CD3, CD8, CD45RO, and FoxP3 varied across indications, showing generally highest values in ganglioneuroblastoma and lowest values in nephroblastoma." (PMID 31922656, 2020). "The aim of the present study was to analyze rs3761548 and rs2232365 FOXP3 polymorphisms, as well as evaluate rs1801157 CXCL12 polymorphism in Wilms’ tumor samples." (PMID 27830498, 2016).
nephrotic syndrome (2 papers, 2014 to 2017). A collection of symptoms that include severe edema, proteinuria, and hypoalbuminemia; it is indicative of renal dysfunction. "Neonatal diabetes and nephrotic syndrome were reported as the only clinical features in the surviving 15-year-old patient with mutation V408M of FOXP3." (PMID 24982679, 2014).
neuropathic pain (2 papers, 2015 to 2016). Chronic pain caused by damage to nerve fibers. "First, to confirm our previous findings, we determined the Foxp3/CD4+ cell ratio in neuropathic pain patients as compared to healthy volunteers." (PMID 27646435, 2016). "Neuropathic pain patients exhibited significantly elevated Foxp3/CD4+ ratios (1.6 ± 0.9 in neuropathic pain vs. 0.8 ± 0.5 in healthy controls; p < 0.05)." (PMID 27646435, 2016).
neutropenia (2 papers, 2015 to 2020). A decrease in the number of neutrophils found in the blood. "FOXP3 was undetectable in one patient (CVID), and RORγt was undetectable in six patients (one CVID, one CID, two neutropenia, one WAS, and one CMC)." (PMID 32670274, 2020). "Notably, FOXP3 was undetectable in one patient (CVID), RORγt was undetectable in six patients (one CVID, one CID, two neutropenia, one WAS, and one CMC), and both were undetectable in four patients (two SCID, one STAT1, and one periodic fever)." (PMID 32670274, 2020).
Omenn syndrome (2 papers, 2019 to 2023). An inflammatory condition characterized by erythroderma, desquamation, alopecia, chronic diarrhea, failure to thrive, lymphadenopathy, and hepatosplenomegaly, associated with severe combined immunodeficiency (SCID). "Depletion of Aire-expressing mTEC and tDCs are in accordance with a dramatic decrease of Foxp3+ nTregs in the thymus of Omenn syndrome patients." (PMID 31679515, 2019).